COPS6 (COP9 signalosome subunit 6)
Description:
Component of the COP9 signalosome complex (CSN), a complex involved in various cellular and developmental processes. The CSN complex is an essential regulator of the ubiquitin (Ubl) conjugation pathway by mediating the deneddylation of the cullin subunits of SCF-type E3 ligase complexes, leading to decrease the Ubl ligase activity of SCF-type complexes such as SCF, CSA or DDB2. Has some glucocorticoid receptor-responsive activity. Stabilizes COP1 through reducing COP1 auto-ubiquitination and decelerating COP1 turnover rate, hence regulates the ubiquitination of COP1 targets.
Synonyms: CSN6; MOV34-34KD
Tractability: PROTAC: ubiquitination databases record sites on it; its protein half-life has been measured.
Gene: Protein-coding gene on chromosome 7 (100,088,948 to 100,093,340, forward strand). Ensembl gene ENSG00000168090.
Subcellular location: Nucleus; Cytoplasm; Cytoplasm, perinuclear region
Subcellular location (Human Protein Atlas): Nucleoplasm
Pathways (Reactome):
DNA Repair: DNA Damage Recognition in GG-NER; Formation of TC-NER Pre-Incision Complex
Metabolism of proteins: Neddylation
Vesicle-mediated transport: Cargo recognition for clathrin-mediated endocytosis
Gene Ontology:
Molecular function: protein binding; metal-dependent deubiquitinase activity; peptidase activity
Biological process: protein deneddylation; protein neddylation; regulation of protein neddylation
Cellular component: COP9 signalosome; cytoplasm; nucleoplasm; nucleus; cytosol; perinuclear region of cytoplasm
Genetic constraint (gnomAD): Loss-of-function variants: 9 observed, 42.08 expected, observed/expected ratio (o/e) 0.21, 90% interval 0.13 to 0.37. The upper end of that interval is the gene's LOEUF score, 0.37, which puts it in group 1 of 6, group 1 being the genes least tolerant of losing a copy. Missense variants: 302 observed, 446.18 expected, observed/expected ratio (o/e) 0.68, 90% interval 0.62 to 0.75. Synonymous variants: 179 observed, 165.73 expected, observed/expected ratio (o/e) 1.08, 90% interval 0.95 to 1.22.
Homologues: Orthologues: chimpanzee COPS6 (100% identical), guinea pig COPS6 (99% identical), pig COPS6 (98% identical), rabbit COPS6 (97% identical), dog COPS6 (97% identical), mouse Cops6 (90% identical), tropical clawed frog cops6 (88% identical), rat Cops6 (82% identical), macaque COPS6 (70% identical), Drosophila melanogaster CSN6 (59% identical), Caenorhabditis elegans csn-6 (32% identical). Paralogues in human: PSMD7 (23% identical), EIF3F (22% identical).
Diseases named in the same sentence as COPS6 in open-access papers:
COPS6 is named in the same sentence as 31 diseases in open-access papers, as found by Europe PMC text mining. Sharing a sentence is not in itself a finding about the gene and the disease. The quoted sentences say what the papers report.
colorectal cancer (9 papers, 2018 to 2025). A primary or metastatic malignant neoplasm that affects the colon or rectum. "A recent study has demonstrated that in colorectal cancer, COP9 signalosome subunit 6 (CSN6) promotes FASN protein stability by counteracting the activity of E3 ligase F-box and WD repeat domain containing 7 β (FBXW7β)." (PMID 39551780, 2024).
breast carcinoma (7 papers, 2013 to 2025). "Moreover, COPS6 was found to be not only a mediator of IL-6 secretion in the tumor microenvironment, but also a negative regulator of CD8+T cells tumor infiltration in breast cancer." (PMID 40040705, 2025).
cervical cancer (6 papers, 2015 to 2023). A primary or metastatic malignant neoplasm involving the cervix. "The positive transcriptional regulation of cathepsin L (CTSL) by the activity of COP9 signalosome subunit 6 (CSN6) deubiquitinase was identified in cervical cancer cells." (PMID 32545524, 2020). "Interestingly, COPS6 depletion showed in vivo efficacy against glioblastoma, cervical cancer, or papillary thyroid carcinoma, through the regulation of several signaling pathways." (PMID 33036275, 2020).
gastric cancer (2 papers, 2020 to 2022). A primary or metastatic malignant neoplasm involving the stomach. "To further explore the microarray data, we evaluated the transcriptional levels of TIPRL, SERINC3, COPS6, and SELM in 40 frozen gastric tissues of gastric cancer patients by real-time PCR." (PMID 32719745, 2020).
cancer (25 papers, 2011 to 2026). A tumor composed of atypical neoplastic, often pleomorphic cells that invade other tissues. "COPS5 and COPS6 can prevent PD-L1 from degrading, thereby maintaining PD-L1 stability in cancer cells." (PMID 38466642, 2024). "The role of COP9 signalosome subunit 6 (CSN6) in regulating cancer stemness was evaluated by organoid formation and limited dilution analysis." (PMID 32225170, 2020). "In addition, high expression levels of COPS5 and COPS6 were found to predict poorer prognosis in cancer patients." (PMID 38466642, 2024). "Therefore, aberrant overexpression of COPS6/COPS9 in HCC cells facilitated cancer cell growth, which may be attributed to the ubiquitination and degradation of p18 and p21." (PMID 38466642, 2024). "COP9 signalosome subunit 6 (CSN6), a key regulator of different E3 ubiquitin ligases, plays oncogenic roles in various cancers." (PMID 41114465, 2026). "Finally, while 15 DUBs were found to be significantly dysregulated in only one type of cancer, 7 (UCHL1, USP9X, USP11, USP10, USP22, COPS5 and COPS6) displayed multiple alterations in two or more tumor types." (PMID 21283576, 2011).
tumor (20 papers, 2011 to 2026). "In seven cases (UCHL1, USP9X, USP11, USP10, USP22, COPS5 and COPS6), dysregulation was observed in more than one tumor type." (PMID 21283576, 2011). "Both COPS6 and COPS9 knockdown also reduced viable HCC cell number after several days in culture as estimated by CCK8 assay, while overexpression significantly increased, suggesting that COPS6 and COPS9 accelerate HCC tumor growth." (PMID 38466642, 2024). "Moreover, previous reports indicated that MUC1, COPS6, HOTAIR, COL6A1 were served as biomarkers for PAAD and had tumor-suppressive or tumor-promoting ability." (PMID 34285140, 2021).
COPS6 also shares sentences with these, for which no sentence is quoted: glioblastoma (5 papers); colon cancer (4); pancreatic cancer (3); papillary thyroid carcinoma (3); glioma (2); leukemia (2); liver cancer (2); lymph node metastases (2); malignant melanoma (2); myeloma (2); alcoholic fatty liver disease (1); cardiac disease (1); hepatocellular carcinoma (1); infection (1); iron deficiency (1); lung carcinoma (1); lymphoma (1); myeloproliferative disorder (1); myocardial hypertrophy (1); non‐alcoholic fatty liver diseases (1); non‐alcoholic steatohepatitis (1); Obesity (1); ovarian carcinoma (1); prostate carcinoma (1); Sepsis (1).